IL33 (interleukin 33)
Diseases named in the same sentence as IL33 in open-access papers (continued):
Sharing a sentence is not in itself a finding about the gene and the disease.
infection (continued). "Finally, the ileum cytokines IL-2, IL-12p70, IL-13, IL-17, GM-CSF, IFN-γ, TNF-α, and IL-33 remained unchanged relative to baseline over the course of infection in both genotypes." (PMID 35985797, 2022). "However, the major cellular source and exact release mechanism of IL-33 during infection-induced thymic involution warrant further investigation." (PMID 36371464, 2022). "Our findings not only demonstrate a mechanism underlying naive T cell dysfunction associated with aging during severe infection but also suggest that IL-33 or ST2 is a promising intervention target to rejuvenate T cell function to better control severe infection." (PMID 36371464, 2022). "Thus, IL-33 modulates MC activation and seems to promote early bacteria-MC interactions upon infection." (PMID 35886897, 2022). "IL-33 is closely involved in pathological process in parasite and pathogen infection." (PMID 36291105, 2022). "However, little is known about IL-5, IL-33 and type 2 alveolar epithelial cells in the course of C. gattii experimental infection." (PMID 36145419, 2022). "Our findings suggest that targeting IL-33 or ST2 may be a promising intervention avenue for rejuvenating T-cell immunity to better control severe infection." (PMID 36371464, 2022). "Our findings not only uncover a link between severe infection-induced IL-33 and thymic involution-mediated naive T cell aging, but also suggest that targeting IL-33 or ST2 is a promising strategy to rejuvenate T cell immunity to better control severe infection." (PMID 36371464, 2022). "Mice undergoing RV-A1B infection alone showed increased mRNA and protein expression of IL-25 (seven days after secondary infection) and IL-33 (one day after secondary infection) compared to sham-infected mice, and heterologous infection with RV-A2 further increased innate cytokine expression." (PMID 36032072, 2022). "Interleukin-33 (IL-33), a nuclear cytokine in the IL-1 family, functions as an “alarmin” that is released from dead cells and exerts proinflammatory or protective effects during various infections." (PMID 36570798, 2022). "In response to infection or tissue injury, IL-33 precursor is cleaved by caspase-1 to form an active secreted IL-33, which in turn activates mast cells, basophils, and group 2 innate lymphoid cells (ILC2) to secrete IL-4, IL-5, and IL-13 via the receptor suppression of tumorigenicity 2 (ST2)." (PMID 35269828, 2022). "The pleiotropic function of IL-33 might be due to different triggering insults, different infection stages, different immune cell types, and related cytokines." (PMID 36570798, 2022). "Indeed, we observed that the re-establishment of IL-17A levels counteracts the strong systemic microbial dissemination elicited by IL-33 treatment during CR infection." (PMID 33654214, 2021). "IL-33 is released in response to tissue damage, and IL-33 release is induced by IL-37 (cathelicidin), which has a protective function against UTIs since its release is significantly decreased in epithelial cells after infection with UPEC." (PMID 34835359, 2021). "To evaluate whether IL-33 deficiency may affect the accumulation of eggs in the intestinal tissues, we compared the number of eggs in intestinal tissues between IL-33−/− and WT mice every 3 weeks from week 6 to week 12 post infection." (PMID 33482904, 2021). "The importance of interleukin (IL)‐33 in promoting effective antiviral immune responses is evident, yet the critical cellular sources of IL‐33 in homeostasis and infection are largely unknown." (PMID 33222176, 2021). "IL-33-treated CR-infected mice showed a dramatic loss of body weight from day 5 on compared to PBS-treated infected mice, with up to 20% reduction at day 8 of infection." (PMID 33654214, 2021). "Therefore, the functions of IL-33 during F. hepatica infection in mice, and in particular the overexpression of its receptor in antigen-presenting cells at the early events of the infection, remain to be elucidated." (PMID 34943041, 2021).
infection (continued). "Indeed, infection with Helicobacter leads to the release of IL-33 from gastric mucosa and subsequent activation of ILC2s, which can secrete IL-5 and enhance the IgA release by B-cells." (PMID 33435303, 2021). "Enhanced expression of IL-33 has been shown in gastric mucosal biopsies from patients positive for H. pylori, and higher concentrations of this cytokine are produced in the acute compared to the chronic phase of the infection." (PMID 34199843, 2021). "Notably, we found increased ST2+ Th17 cell frequencies in the colon of IL-33-treated naïve mice and, to a lesser extent, during CR infection." (PMID 33654214, 2021). "During viral infection, IL-33 is vital for Th1 responses and infection resolution." (PMID 33815404, 2021). "Since IL-33 treatment does not impair the immune response in the late phase of CR infection, it is likely that IL-17A has the power to counterbalance the early pathogenic potential of IL-33 within the gut." (PMID 33654214, 2021). "The functional role of IL-33 has thus expanded from infection to inflammation and metabolic disease, which might also partly explain why sST2 remained a significant predictor of MACEs in patients both with and without T2DM." (PMID 33608010, 2021). "There were no obvious differences of liver injury caused by infection between wild-type and IL-33−/− mice with HPCs’ expansion." (PMID 34674752, 2021). "This may explain why IL-33 treatment in the later phase of infection, when the differentiation of Th17 cells already has taken place, does not appear to affect CR-mediated immunopathology." (PMID 33654214, 2021). "To address whether IL-17A controls IL33-mediated immunopathology in our model, we applied IL-17A to IL-33-treated CR-infected mice from day 3 post infection on and characterized disease progression." (PMID 33654214, 2021). "In addition, we addressed the effect of exogenous IL-33 application on REG3γ expression in vivo during acute CR infection." (PMID 33654214, 2021). "Therefore, we believe that it is necessary to understand the immunological and pathophysiological mechanisms related to the IL-33/ST2 pathway during infection by T. canis." (PMID 34324507, 2021). "Nonetheless, IL-33 treatment during CR infection induced a low percentage of ILC2 to the detriment of ILC3, which may affect the subsequent development of an efficient adaptive immune response." (PMID 33654214, 2021). "In addition, compared to RV-A1B, RV-C15 infection induced significantly higher protein expression of IL-25, IL-33 and TSLP." (PMID 33968043, 2021). "Evidence obtained in human and mice have revealed that IL-33 is released early after viral challenge (within 2 days of infection), and predominantly in areas of acute lung inflammation where it drives immune cellular influx and de novo il-33 gene expression in lung cells." (PMID 34960788, 2021). "Interestingly, IL-33 treatment resulted in significantly higher FITC concentrations in the serum, indicating enhanced gut permeability, an effect that was strengthened when IL-33 was applied during infection." (PMID 33654214, 2021). "Treatment of infected mice with exogenous IL-33 confirmed the protective effects of IL-33 and highlighted the impact on the recruitment of inflammatory monocytes to sites of infection and the subsequent upregulation of iNOS, a process required for the control of T. gondii." (PMID 33929319, 2021). "Moreover, the inflammatory infiltrates in IL-33−/− mice contained fewer eosinophils than those in WT mice at the sixth week of infection." (PMID 33482904, 2021). "Moreover, infection with T. gondii promotes stromal cells to produce IL-33, which synergizes with IL-12 to amplify IFNγ production by ILCs for protection." (PMID 34938670, 2021). "Whether it is released during an EIV infection in horses, or whether asthmatic horses express higher levels of IL-33 is currently unknown." (PMID 34960788, 2021).
infection (continued). "IL‐33, belonging structurally to the IL‐1 superfamily, is known as an “alarmin” that acts like other damage‐associated molecular pattern (DAMP) molecules upon tissue damage, infection, or necrosis." (PMID 33222176, 2021). "Thus, CR-infected and naïve mice were treated with IL-33 on the day of infection and every second day for the duration of the experiment." (PMID 33654214, 2021). "During infections, depending on the organ involved, IL-33/ST2 signaling might induce the necessary immune response to control the infectious foci, which might be a Th1 or Th2 type of response." (PMID 32353980, 2020). "In this context, Th2 cells have been shown to be critical for IL‐33‐dependent infection immunity." (PMID 32566227, 2020). "IL-33 activation of a Th2 cellular immune response would be detrimental in patients suffering from leishmaniasis, and inhibition of this signaling has been demonstrated to abrogate infection within the liver of VL." (PMID 32363166, 2020). "Thus, IL-33 has dual effects on infection, inflammation, and diseases of the CNS raising the question of the cellular and immunomodulators involved." (PMID 32917228, 2020). "Similarly, in Strongyloides venezuelensis lung-stage infection, neutrophil recruitment is IL-33-independent." (PMID 32695116, 2020). "If microglia normally respond to IL-33 earlier in infection, our results indicate that astrocyte responses to IL-33, or additional MyD88-dependent signals, may compensate for the lack of il1rl1-signaling in microglia." (PMID 33108405, 2020). "Here, we show that IL-33 is expressed by oligodendrocytes and astrocytes during T. gondii infection, is released locally into the cerebrospinal fluid of T. gondii-infected animals, and is required for control of infection." (PMID 33108405, 2020). "How AXPN upregulates IL-33 expression remains to be determined, but our results indicate that AXPN-induced IL-33 resulted in enhanced neutrophil infiltration to the site of infection, ultimately leading to improved bacterial killing and early resolution of inflammation." (PMID 32156806, 2020). "Interestingly, one application of IL-33 immunomodulation currently being explored is that of helminth therapy: the intentional ingestion of helminth ova or their larvae to induce infection." (PMID 32363166, 2020). "Moreover, the functions of IL-33 in enhancing adaptive type 2 immunity and thereby improving larval attack in secondary infections will be different from the rapid and innate function IL-33 exerts during the first week of infection that we study here." (PMID 33351862, 2020). "Infecting with 10 cysts of Me49 parasite intraperitoneally, we do not observe significant mortality or pathology in wildtype mice, but nonetheless, IL-33 signaling could potentiate immunopathology during more severe infections." (PMID 33108405, 2020). "Beyond its role in iron homeostasis and the response to erythrocyte damage, IL-33 might also be involved in other immunological properties of RPMs, including the response to infections." (PMID 32272082, 2020). "In IRF7-/- mice, the peak of infection (7 dpi) was associated with increased nuclear-to-cytoplasmic HMGB1 translocation in the epithelium, increased IL-33 levels in the airway lumen, and the infiltration of neutrophils, which can process IL-33 to a more biologically active form." (PMID 32658914, 2020). "IL-33 most likely plays a key role in human disease, as evidenced by increased levels of the cytokine or its decoy receptor sST2 during both viral and bacterial infections." (PMID 30949175, 2019). "First, we asked whether increasing IL-33 levels in the gut alters disease severity during infection." (PMID 31221971, 2019). "Given that IL-33 is released upon cell death, it is likely that toxin-mediated apoptosis or inflammasome-mediated pyroptosis are required for IL-33 release and activation of ILC2s during infection." (PMID 31221971, 2019).
infection (continued). "However, we found that the level of IL-33 in BAL fluids was much less than that of IL-6 and IL-12p40, and the survival of IL-33-deficient mice was similar to those of normal mice post-infection." (PMID 31509992, 2019). "Recently, focus has increased on whether the role of infections in the tumorigenic effect of IL-33 determines comparable results." (PMID 31130612, 2019). "We also noticed that IL-33 treatment reduced epithelial barrier disruption during infection." (PMID 31221971, 2019). "It is hypothesized that host Hsp60 and IL-33 can be both targeted by antibodies stimulated by HP CagA-positive strain infection, which may affect the gastric inflammatory response." (PMID 32064263, 2019). "Indeed, protective IL-33 treatment led to a significant increase in ST2+ ILC2s within the colon lamina propria during infection." (PMID 31221971, 2019). "Possibly, IL-33, secreted principally by the epithelium, fibroblasts and endothelium, released after cell damage caused by S. mansoni eggs will bind to its receptor (ST2) and drives the T helper 2 response needed to contain the infection." (PMID 31849991, 2019). "Notably, this IL-33 treatment regimen reduced mortality following infection with R20291 as evidenced by the increased survival (70% with IL-33 treatment vs. 30% without)." (PMID 31221971, 2019). "Infection of the lung by the intestinal nematode S. venezuelensis increases the number of IL-33-producing alveolar epithelium type II (ATII) cells in wild type and Rag2-deficient mice, which develop eosinophilic inflammation and goblet cell hyperplasia (Loeffler syndrome)." (PMID 30717382, 2019). "IL-33-mediated protection was also not caused by a reduction in toxins A/B or CDT, as IL-33 treatment mice had equivalent toxin levels over the course of acute infection when peak disease occurred." (PMID 31221971, 2019). "In agreement with previous findings, reinfection of mice by S. venezuelensis induced only weak Il33 mRNA expression compared with primary infection and was unable to induce Th2 cytokine expression despite the relatively high numbers of ILC2s remaining in the lungs of Sv-exp mice." (PMID 30283458, 2018). "Based on previous findings, it is plausible that high baseline IL33 expression in BN could be responsible for the attenuation of type I IFN/neutrophilic responses that were observed in this strain following vMC0 infection." (PMID 30150981, 2018). "Our findings confirmed that IL-33-producing cells are located in the periphery of egg granulomas where activated HSCs produce excess collagen, and that expression of IL-33 in primary HSCs is significantly elevated after infection." (PMID 29554131, 2018). "After cell stress or necrosis, IL-33 is released into the extracellular space and functions as an endogenous danger signal that alerts the immune system of tissue damage during trauma or infection." (PMID 30483263, 2018). "In addition, IL-33, an alarmin released upon barrier disruption, was slightly more induced during wildtype infection." (PMID 29390040, 2018). "We found that expression of miR-203-3p began to decrease in the liver at day 32 post-infection, reaching its lowest levels at day 42 and 52; in contrast, the level of Il33 mRNA was maintained during the early stage of infection, then significantly elevated by day 42 post-infection." (PMID 29554131, 2018). "Importantly, we show that miR-203-3p targets IL-33, an inducer of type 2 immunity, in HSCs to regulate the expansion and IL-13 production of hepatic ILC2s during infection." (PMID 29554131, 2018). "Consistent with our findings in humans, IL-33 mRNA and protein increase was only detected in gastric mucosa of WT H. pylori-strain-infected mice, reaching a peak 56 days post infection (p.i.), indicating a crucial role for cagA in the induction of IL-33 during H. pylori infection." (PMID 29691371, 2018).
infection (continued). "We show that miR-203-3p targets interleukin-33 (IL-33), an inducer of type 2 immunity, in hepatic stellate cells to regulate the expansion and IL-13 production of hepatic group 2 innate lymphoid cells during infection." (PMID 29554131, 2018). "Moreover, naive BN showed a Th2 bias following infection with vMC0, as shown by an influx of alternatively activated macrophages (MGL1/ARG1) with parallel upregulation of Th2-associated cytokines (IL25/IL33)." (PMID 30150981, 2018). "Importantly, our study revealed other important aspects of the role of IL-33 in the regulation of type 2 pathology after infection." (PMID 29554131, 2018). "Importantly, our data indicate that miR-203-3p targets IL-33, an inducer of type 2 immunity, in HSCs to regulate the expression of IL-13 in hepatic group 2 innate lymphoid cells (ILC2s) during infection." (PMID 29554131, 2018). "Furthermore, S. venezuelensis infection-induced resistance to infection by N. brasiliensis was abrogated in Il33−/− mice." (PMID 30283458, 2018). "On the other hand, IL-33 stimulation of ILC2s could be beneficial in intestinal inflammation outside the setting of infection for instance in cases of helminth intestinal infection." (PMID 30405626, 2018). "Moreover, Treg cells produce amphiregulin to prevent lung damage in response of alarmin IL-33 after infection with influenza virus." (PMID 29977243, 2018). "It has been well established that some viruses alter the expression of IL-33 during infection." (PMID 28448566, 2017). "Thus, PbA-infection induced an inflammatory response in the hippocampus, involving a strong IL-33 expression by oligodendrocytes, and this response was dependent on a functional IL-33/ST2 pathway." (PMID 28448579, 2017). "Indeed, we document exacerbated IL-33 expression by astrocytes and oligodendrocytes after PbA-infection in WT mice." (PMID 28448579, 2017). "Hence, the activation of IL-33 signaling is essential for immunity to infection, requiring neutralization of helminth EVs to take place in wild-type mice for parasite expulsion." (PMID 28538175, 2017). "Therefore, the glial cell inflammatory response observed in hippocampus after PbA-infection requires the presence of a functional IL-33/ST2 pathway." (PMID 28448579, 2017). "Gastro-intestinal helminth infections trigger the release of interleukin-33 (IL-33), which induces type-2 helper T cells (Th2 cells) at the site of infection to produce IL-13, thereby contributing to host resistance in a T cell receptor (TCR)-independent manner." (PMID 29045902, 2017). "The absence of IFNγ induction in IL-33 KO mice could be explained partially by the reduction of these cells in IL-33 KO mice during early infection at 48 h PI and reconstitution of NK or NKT cells at 72 h of PI." (PMID 28607531, 2017). "At the site of infection, Th2 cells secrete IL-13 upon exposure to IL-33." (PMID 29045902, 2017). "Thus, we confirm not only that IL-33 is expressed in astrocytes and oligodendrocytes in the brain, but that this expression is increased in hippocampus 7 days post PbA-infection." (PMID 28448579, 2017). "However, IL-33 induced higher levels of IL-13 production in spleen and liver of mice with mixed infected than in male-only infection." (PMID 27445267, 2016). "In our model, the protective role of IL-33 is directly related to the local T cell response modulation, since IL-33 deficiency leads to augmented Th1 local immune response, with IFN-γ overproduction and increased death following infection with ROCV." (PMID 27334012, 2016). "Both thymic stromal lymphopoietin (TSLP) and IL-33 levels were increased 12 hours after infection." (PMID 27156176, 2016). "Of interest, are the differences in the response to IL-33 between mixed and male only-infection." (PMID 27445267, 2016).